GRPR (gastrin releasing peptide receptor)
Diseases named in the same sentence as GRPR in open-access papers (continued):
Sharing a sentence is not in itself a finding about the gene and the disease.
tumor (continued). "Additionally, different tumor characteristics between PCa and BCa, including GRPR expression density and heterogeneity, and the level of GRPR expression in physiological tissues, might affect the imaging efficacy of radiopharmaceuticals, like [99mTc]Tc-DB8." (PMID 41155959, 2025). "However, there is also some degree of GRPR expression on membranes of tumor-infiltrating immune cells, which might explain the uptake of [99mTc]Tc-DB8 in ER-negative tumors." (PMID 40871022, 2025). "Thus, GRPR activation probably occurs in primary tumours in these tissues." (PMID 40500450, 2025). "A patient with a PSMA-negative scan could still harbor a tumor that tests positive for GRPR." (PMID 41226028, 2025). "However, agonists can be internalized upon binding to GRPR and lead to a longer tumor retention, which might be preferable especially for the development of radiotherapeutic agents." (PMID 38305955, 2024). "Notably, GRPR inhibition using antagonist drugs significantly diminished tumor invasion." (PMID 39768218, 2024). "It was previously demonstrated that, as targeting agents, GRPR antagonists are superior to GRPR agonists because of the former’s higher number of binding sites, higher metabolic stability, or stronger interaction with the receptor, which explains the continuous tumor retention over time." (PMID 39327021, 2024). "However, agonists can be internalized upon binding to GRPR and potentially lead to longer tumor retention, which might be preferable, especially for use in the development of radiotherapeutic agents." (PMID 36838968, 2023). "Moreover, since the use of GRPR antagonists has been shown to lead to higher levels of tumor accumulation, the more agonistic properties of the developed dual-modality probes could partly explain the observed decrease in total binding." (PMID 37046825, 2023). "The first-generation GRPR-targeting agonists showed some promise but the second-generation antagonists were found to be more beneficial; they not only demonstrated less off-target effects but also a higher tumour uptake, more advantageous pharmacokinetics, and higher tumour-to-background ratios." (PMID 36672390, 2023). "Previous studies dealt with the evaluation of 44Sc-appended avb3 integrin–affine Arg-Gly-Asp (RGD) tripeptides, GRPR-selective aminobenzoyl–bombesin analogue (AMBA), and hypoxia-associated nitroimidazole derivatives in the identification of various cancers using experimental tumour models." (PMID 37108559, 2023). "Whether loss of GRPR expression as indicated by low or absent 68Ga-NeoBOMB1 uptake is a sign of tumor dedifferentiation and worsening in prognosis remains unclear at this point but may warrant further investigation in larger cohort." (PMID 36428467, 2022). "Moreover, activity levels in GRPR-positive organs were noticeably reduced (pancreas by 70% and stomach by 40%) while tumor uptake was only decreased by 20% compared to [99mTc]Tc-N4-asp-MJ9 at 1 h p.i., pointing to a beneficial impact of the Bta-for-Trp8 substitution on clearance kinetics." (PMID 36145354, 2022). "Furthermore, GRPR radioantagonists often display attractive pharmacokinetic profiles in preclinical models and in patients, as a combined result of rapid clearance from physiological tissues and good retention in tumor sites." (PMID 32731473, 2020). "Several preclinical and clinical literature sources have revealed that non-internalizing GRPR radioantagonists could successfully target and are sufficiently retained in overexpressed GRPR tumor lesions while rapidly clearing from physiologic tissues and organs." (PMID 33335885, 2020). "Therefore, combined targeting of both PSMA and GRPR could lead to a high tumor uptake during all disease stages." (PMID 31671763, 2019).
tumor (continued). "The aim of our study is to evaluate whether we can also improve tumor targeting of [111In]SB3 by co-administration of PA to potentially use the radiotracer for pre-operative SPECT/MRI and ultimately for intra-operative radio-guided tumor detection of GRPR-expressing tumors and/or metastases as well." (PMID 29556947, 2018). "The comparison of GRPR SPECT and PSMA SPECT revealed higher tumor uptake for [99mTc]Tc-DB8 in the primary lesion in the prostate gland." (PMID 41155959, 2025). "The interaction of GRPR on the surface of GRP-expressing cells forms an autocrine loop, promoting tumor growth." (PMID 41266536, 2025). "We evaluated the potential of these 177Lu-labeled ligands as GRPR-targeted therapeutic agents by SPECT imaging and ex vivo biodistribution studies in GRPR-expressing tumor-bearing mice and dosimetry calculation." (PMID 40283887, 2025). "Both showed excellent GRPR-specific uptake and low off-target accumulation, but the NOTA derivative exhibited superior tumor retention at 24 h." (PMID 41251982, 2025). "E-cadherin is known to be tumour suppressor in breast and stomach cancers, in which GRP is abundantly produced and activates GRPR." (PMID 40500450, 2025). "For a proof-of-concept study, the two tumor-specific membrane proteins PSMA and GRPR were selected because they are well-known targets for clinical imaging of PCa." (PMID 40732291, 2025). "Co-injection of a 100-fold molar excess of unlabeled NOTA-PEG2-RM26 significantly (p < 0.0001) reduced tumor and pancreas activity uptake of [177Lu]Lu-PKB2 and [177Lu]Lu-PKB3 and at 2 h pi, confirming the GRPR specificity of both peptides." (PMID 41231375, 2025). "The significantly reduced tumor uptake of [177Lu]Lu-TacsBOMB5, [177Lu]Lu-LW01110, and [177Lu]Lu-LW01142 in the blocked mice demonstrates their GRPR-targeting specificity." (PMID 40283887, 2025). "With high in vivo stability, great tumor uptake, and excellent tumor-to-background imaging contrast, [68Ga]Ga-LW02060 is a promising tracer for clinical translation to detect GRPR-expressing cancer." (PMID 40006047, 2025). "To assess the significance of GRPR gene expression in LUAD, we compared its expression levels between normal and tumor tissues." (PMID 39768218, 2024). "Several investigations have reported the overexpression of GRPR in non-small cell lung cancer (NSCLC) and its potential role in promoting tumor growth." (PMID 38279185, 2024). "With good tumor uptake and tumor-to-background imaging contrast, [68Ga]Ga-LW01158 is promising for detecting GRPR-expressing lesions with PET." (PMID 38794191, 2024). "The study revealed a significant correlation between radioligand binding of GRPR and SSTR and the expression of receptor mRNA in tumor tissue." (PMID 38279185, 2024). "In the T47D (GRPR+) cell line, both 64Cu-NOTA-RGD-BBN and 68Ga-NOTA-RGD-BBN exhibited tumor uptake at 1 h of 2.33 ± 0.59%ID/g and 2.78 ± 0.87%ID/g, respectively." (PMID 38708130, 2024). "With excellent tumor uptake and tumor-to-background contrast, [68Ga]Ga-LW01110 is promising for detecting GRPR-expressing cancer lesions with PET." (PMID 38305955, 2024). "The potential of these ligands for detecting GRPR-expressing cancer was evaluated by an in vitro competition binding assay, PET imaging, and ex vivo biodistribution studies in PC-3 tumor-bearing mice." (PMID 38794191, 2024). "As expected, the higher GRPR-affinity and better metabolic stability of [111In]In-AU-SAR-M2 translated in higher tumor uptake in PC-3 xenograft-bearing mice." (PMID 38366299, 2024). "In addition, GRPR acts as a paracrine signaling pathway with mitogenic effects in PC, increasing the expression of metalloproteinases that remodel the extracellular matrix of the tumor microenvironment, allowing a greater capacity for tumor growth and invasion, resulting in mCRPC." (PMID 39598482, 2024).
tumor (continued). "The expression of GRPR, PSMA, and NTR1 in PC-3 and LNCaP tumor tissues was examined by Immunohistochemical staining, and the results were consistent with PET/CT imaging." (PMID 38880858, 2024). "The tumor uptake appears to be significantly reduced in the third mouse co-injected with excess NT and [Tyr4]BBN for a double NTS1R/GRPR-blockade." (PMID 39339259, 2024). "All 68Ga-labeled tracers were successfully used to visualize PC-3 tumor xenografts in their PET images, confirming good GRPR targeting capabilities of these tracers." (PMID 38305955, 2024). "Overall, the labeling groups, chelating agents, and isotopes exerted profound effects on tumor targeting and in vivo kinetics of RGD-BBN tracers that simultaneously recognize dual integrin αvβ3 and GRPR." (PMID 38279185, 2024). "111In-BQ7812 and 68Ga-BQ7812, bispecific molecules consisting of a urea-based PSMA inhibitor combined with the GRPR-antagonist RM26 were successfully evaluated to image tumor-bearing mice (PSMA- and GRPR-positive)." (PMID 37835533, 2023). "Both [68Ga]Ga-TacBOMB2 and [68Ga]Ga-TacBOMB3 clearly visualized the PC-3 tumor xenografts in their PET images, which confirms the good targeting capabilities of both tracers to GRPR-expressing tumors." (PMID 36838968, 2023). "The SPECT/CT images of tumor-bearing mice after injection of [111In]In-AU-RM26-M1 were in agreement with the biodistribution profile, with clear visualization of the GRPR-positive tumors." (PMID 37509170, 2023). "Among all collected organs, the GRPR-expressing pancreas showed the highest radiotracer uptake with both [177Lu]Lu-NeoB and [177Lu]Lu-RM2 at the 1 h time point, resulting in the lowest tumor-to-organ ratio for this organ." (PMID 37584725, 2023). "More recently, a bispecific iron oxide NPs 68Ga-mNP-N1/2 was synthesized for PET/MR dual-modality imaging of PCa tumours overexpressing PSMA or/and GRPR." (PMID 37241862, 2023). "Applying GRPR-blocking experiment with BBN, we managed to confirm the specific tumor-targeting efficiency of the investigated radioconjugates." (PMID 36077458, 2022). "Concluding, the authors were able to demonstrate that the use of GRPR- and NPY Y1-specific HBPL were indeed beneficial to in vivo tumor uptake and visualization, compared to monospecific agents." (PMID 35744852, 2022). "For all these reasons, we suggest that there is a high probability that the tumor and pancreas uptake of the novel [99mTc]Tc-N4-conjugated MJ9 analogues is GRPR-specific." (PMID 36145354, 2022). "High tumor-to-normal-tissues ratios at 1, 4, and 24 h showed selective uptake of [64Cu]Cu-SAR-BBN to GRPR expressing PC-3 tumors as compared to other tissues such as muscle, liver, and kidney." (PMID 35745647, 2022). "The use of tumour-specific tracers, targeting, for example, ER (e.g. [18F]FES), HER2 (e.g. [68Ga]ABY-025), PARP (e.g. [18F]SuPAR), FAP (e.g. [68Ga]FAPI) or GRPR (e.g. [68Ga]RM2) are likely to further improve the diagnostic accuracy of FAR." (PMID 33738563, 2021). "67Ga/177Lu-DOTA-PESIN showed high uptake in the human prostate tumor xenografts and in murine GRPR-positive organs, PET images demonstrated that 68Ga-DOTA-PESIN accumulates predominantly in the PC-3 tumor, pancreas, and kidneys." (PMID 33809749, 2021). "In comparison to other GRPR-targeting agents, [177Lu]Lu-NeoB favorably compares with GRPR-radioagonists [177Lu]Lu-AMBA and [177Lu]Lu-BBN8, which exhibited tumor-to-pancreas and tumor-to-gastro-intestinal tract ratio < 1 at 24 h p.i." (PMID 33801382, 2021). "The aim of this study was to develop a GRPR-targeting ligand based on a GRPR antagonist and an ABD that would have prolonged blood circulation time and, therefore, increase the tumor uptake of the ligand." (PMID 33081166, 2020). "Bombesin (BBN) peptide has shown high binding affinity and specificity to target the GRPR; efforts have been focused on developing radiolabeled or fluorescent dye labeled BBN analogues for tumor imaging and therapy." (PMID 32651409, 2020).
tumor (continued). "In particular, for [99mTc]Tc-DB4, these treatments were compared in mice bearing GRPR-positive human prostate adenocarcinoma PC-3 xenografts and for [111In]In-SG4, in mice bearing a double A431-CCK2R((+/−)) tumor model." (PMID 33256013, 2020). "However, further investigations are needed to develop an optimal PSMA/GRPR-targeting heterodimer with high affinity to both targets, together with a preferable pharmacokinetic profile with high uptake and long retention in the tumor, low uptake in normal tissue and fast blood clearance." (PMID 32630176, 2020). "In the in vivo biodistribution study of [111In]In-BQ7812 in PC3-pip tumor-bearing mice (PSMA and GRPR positive), the activity uptake was two-fold higher in the tumor and three-fold higher in kidneys than for [111In]In-BQ7800." (PMID 32630176, 2020). "Thus, the combination of GRPR- and αvβ3-specific peptides to radiolabeled heterodimers should be able to increase tumor visualization specificity and sensitivity for the mentioned tumor entities, and several GRPR- and αvβ3-bispecific radiotracers have been developed." (PMID 32751666, 2020). "GRPR and other protein expressions distinctly increased with BN4 peptide treatment compared to BN3 and BNS; more metastasis and tumor growth was promoted via HIF-1α which increased angiogenesis." (PMID 30887136, 2019). "It should be noted that tumor and pancreas values achieved by 111In-SB4 at 4 h pi were significantly reduced after coinjection of excess [Tyr4]BBN, suggesting a GRPR-mediated uptake (p < 0.001)." (PMID 30871262, 2019). "Conjugates suitable for SPECT imaging generally demonstrated high tumor-to-organ ratios and together with the new generation of SPECT cameras, indium labeled GRPR antagonists should provide images with high contrast." (PMID 31745219, 2019). "All these results suggest that for the BN4-treated system, hypoxia is induced leading to more tumor growth and more angiogenesis (VEGF, HIF-1α, and GRPR) and more cell proliferation (PCNA and Ki67) that leads to enhanced metastasis of tumor cells." (PMID 30887136, 2019). "Tumor uptake at 4-h pi was significantly lower in the animals treated with excess [Tyr4]BBN (0.62 ± 0.24%ID/g; p < 0.001), suggestive of a GRPR-mediated process." (PMID 30897789, 2019). "The gastrin-releasing peptide receptor (GRPR), overexpressed on various tumor types, is an attractive target for receptor-mediated imaging and therapy." (PMID 29556947, 2018). "The mitotic activity of GRP in human tumours is largely mediated by the G-protein-coupled receptor BB2, also known as GRP-receptor (GRPR); interestingly, the interference with GRPR-mediated functions produces significant anti-mitotic effects." (PMID 30543050, 2018). "Co-administration of PA increased in vivo tumor targeting capacity of [111In]SB3, making this an attractive combination for GRPR-targeted tumor imaging." (PMID 29556947, 2018). "Due to tolerable in vivo stability and reasonable tumor uptake, PESIN peptide is regard as one of the most promising ligands to gastrin releasing peptide receptor (GRPR), which is overexpressed on several tumor types." (PMID 29124984, 2017). "From the six paired samples analyzed, two cases showed specific binding of the GRPR and SSTR2 radioligands in both the primary tumor and the lymph node metastases." (PMID 28107508, 2017). "Binding of GRPR and SSTR radioligands to tumor tissue correlated significantly with receptor mRNA expression." (PMID 28107508, 2017). "The total number of binding sites (the sum of GRPR and integrin) for 99mTc-RGD-BBN would significantly increase as compared to the monomeric counterparts in the dual-receptor positive tumor models, which would lead to improve in vivo tumor targeting efficacy." (PMID 25849333, 2015). "Blocking studies by biodistribution in PC3 tumor-bearing mice were realized to validate the results obtained by PET imaging, confirming the GRPR-mediated uptake of the tracer." (PMID 22333272, 2012).
tumor (continued). "Overall, our data show that 64Cu/NOTA-dimer 2 presents similar affinity for GRPR and PC3 uptake in vivo, greater tumor retention in vitro and in vivo but also higher uptake in the liver and kidney when compared to 64Cu/NOTA-monomer." (PMID 22333272, 2012). "Importantly, the decreased tumor growth was associated with antagonist-induced decreases in p-Akt levels and COX-2 expression suggesting, together with the data presented herein, that GRPR blockage may be an effective means of decreasing COX-2 expression within receptor-positive tumor tissue." (PMID 21745389, 2011). "68Ga-RM2 is a GRPr antagonist that is conjugated to a DOTA molecule to facilitate conjugation chemistry with 111In and 68Ga for SPECT and PET imaging, respectively, and has shown high tumor to background uptake." (PMID 40863874, 2025). "A GRPR expression level as low as 10% was sufficient to distinguish positive from negative tumor samples (p < 0.0001)." (PMID 41266536, 2025). "[177Lu]Lu-TacsBOMB5, [177Lu]Lu-LW01110, and [177Lu]Lu-LW01142 showed significantly higher tumor/pancreas ratios at all five time-points compared with [177Lu]Lu-AMBA, suggesting better biodistribution profiles and lower off-target uptake of our GRPR-targeted ligands." (PMID 40283887, 2025). "The GRP modulates various physiological processes by binding to its receptor, the gastrin-releasing peptide receptor (GRPR), and influences functions such as central nervous system regulation, gastrointestinal activity, tumor progression, immune cell modulation, and inflammatory responses." (PMID 40509291, 2025). "This suggests that hypoxia-induced GRPR signalling may cooperate with HIF-1α–regulated survival pathways, further supporting GRPR as a critical mediator of tumour adaptation under low-oxygen conditions." (PMID 41226822, 2025). "Together, our study provides compelling evidence that BU peptide antagonises GRPR by competitively blocking GRP-induced receptor activation and downstream PI3K/Akt and MAPK/ERK signalling, thereby inducing apoptosis and suppressing tumour cell viability." (PMID 41226822, 2025). "On the other hand, the rich surface functional groups of GO facilitate the binding with targeting ligands (such as GRPR antagonistic peptides, folic acid, RGD peptides, etc.), enabling targeted delivery to tumor tissues and enhancing the specificity and accumulation efficiency of PDT." (PMID 41155020, 2025). "The study reinforces the growing interest in antagonist-based BRLs for imaging GRPR, where internalization is not a prerequisite for effective tumor visualization." (PMID 40869454, 2025). "Autoradiography of tumor lesions displayed varied expression levels of GRPR, with 4 cases showing negative expression." (PMID 38279185, 2024). "Amongst the radiolabeled GRPR-antagonists developed in recent years, [99mTc]Tc-DB15 has especially attracted our attention by combining a high GRPR-affinity, resistance to NEP in the bloodstream, good tumor uptake and excellent tolerability in patients." (PMID 38366299, 2024). "A good in vivo GRPR-targeting capability of [68Ga]Ga-SB3 and [68Ga]Ga-LW02050 was confirmed as PC-3 tumor xenografts were clearly visualized in the PET images, while [68Ga]Ga-LW02075 showed a lower uptake in PC-3 tumor xenografts." (PMID 38999054, 2024). "With a significantly lower uptake in the pancreas and a comparable tumor uptake compared with the clinically validated [68Ga]Ga-RM2, [68Ga]Ga-LW01158 is a promising radiopharmaceutical for detecting GRPR-expressing lesions with PET, especially for lesions in or adjacent to the pancreas." (PMID 38794191, 2024). "The uptake in GRPR-expressing PC-3 tumor xenografts was reduced by >80% with the co-injection of 100 μg of nonradioactive standard, confirming the tumor uptake of [68Ga]Ga-LW01158 is specific." (PMID 38794191, 2024).